BRAF (B-Raf proto-oncogene, serine/threonine kinase)
Diseases named in the same sentence as BRAF in open-access papers (continued):
Sharing a sentence is not in itself a finding about the gene and the disease.
metastatic melanoma (continued). "Although innovative therapies such as BRAF inhibitor and immune checkpoint inhibitor have gained remarkable advances, metastatic melanoma remains an incurable disease for its notorious aggressiveness." (PMID 29542252, 2018). "While immunotherapy including checkpoint inhibitors and targeted therapies (BRAF/MEK inhibitors) are options for patients with metastatic melanoma, many patients experience progression." (PMID 30400822, 2018). "Even though the gold standard method to assess BRAF status in patients with metastatic melanoma is based on molecular assays, the high costs and expertise required for the molecular assay is responsible for the limited use of the test." (PMID 30488019, 2018). "Treatment of metastatic melanoma targeting genetically activated oncogene pathways (BRAF/NRAS/KIT pathways) and so-called immune-checkpoints have significantly improved overall survival rates of metastatic melanoma patients in recent years." (PMID 29614062, 2018). "About 50% of patients with metastatic melanoma carry a mutation in the serine-threonine protein kinase B-RAF, mostly BRAF V600E or V600K." (PMID 30344946, 2018). "The framework described in this study is applied to three treatments currently used within the metastatic melanoma setting, vemurafenib (BRAF/CRAF inhibitor), dabrafenib (BRAF inhibitor) and trametinib (MEK inhibitor)." (PMID 29222604, 2018). "Although involved in the regulation of T cell proliferation and survival, selective BRAF inhibitors have been shown to increase CD8+ lymphocytes in human metastatic melanoma models." (PMID 29763623, 2018). "In patients with BRAF mutant metastatic melanoma, high response rates are observed after treatment with BRAF/MEK inhibitors, although the duration of response is short lasting due to adaptive therapy resistance." (PMID 30100909, 2018). "Trametinib is a reversible and highly selective allosteric inhibitor of MEK1 and MEK2 kinase activity and has been developed and studied in BRAF-mutant metastatic melanoma." (PMID 29464099, 2018). "In patients with metastatic melanoma, BRAF inhibitors have shown to decrease the immunosuppressive cytokines with resultant increased CD8+ T cell tumor infiltration and antitumor immunity." (PMID 30100909, 2018). "Chromosomal alterations, such as BRAF mutations lead to constitutive activation of the mitogen-activated protein kinase (MAPK) pathway, a prominent signaling pathway in human metastatic melanoma." (PMID 29541385, 2018). "Lastly, the widespread use of immune checkpoint inhibitors and BRAF targeted therapy revolutionized the treatment of metastatic melanoma in the years following closure of these trials." (PMID 29773080, 2018). "The mutation status of the BRAF and NRAS genes in tumor tissue is used to select patients with metastatic melanoma for targeted therapy." (PMID 30546839, 2018). "The survival of patients with metastatic melanoma has improved with treatment with BRAF and MEK inhibitors or with immunotherapy such as anti-PD-1 or anti-CTLA-4 antibodies." (PMID 30546839, 2018). "The development of molecularly targeted therapies such as the BRAFi vemurafenib or dabrafenib and especially the combined BRAF and MEK inhibition improved the prognosis for BRAF-mutated metastatic melanoma patients." (PMID 30206212, 2018). "A 50 year-old female who presented in 2011 with an axillary mass, which on removal was shown to be a BRAF wild-type metastatic melanoma." (PMID 30107850, 2018). "Determination of BRAF status is important for the therapeutic management of patients with metastatic melanoma." (PMID 30181812, 2018). "The three studies were conducted in a similar patient population, BRAF mutant positive metastatic melanoma patients, with RECIST criteria used for imaging data collection." (PMID 29222604, 2018). "BRAF and MEK inhibition is efficient in patients with BRAF V600-mutated metastatic melanoma, but due to acquired resistance the duration of response (DoR) is often only short-lived." (PMID 30344946, 2018).
metastatic melanoma (continued). "We investigated the feasibility of the IdyllaTM assay for detection of BRAF and NRAS mutations in cfDNA of 19 patients with metastatic melanoma at baseline and during the course of treatment." (PMID 30546839, 2018). "Protein expression in a cohort of 32 drug naïve BRAF/NRAS metastatic melanoma specimens was examined." (PMID 30116025, 2018). "The most thorough analysis of the relationship between the oncogenic BRAF signaling and miRNAs expression and function in metastatic melanoma was carried out by Couts at al." (PMID 28118616, 2017). "We report a unique case of glomerulonephritis with renal granulomatous vasculitis in a patient diagnosed with metastatic melanoma treated with BRAF and MEK inhibitors." (PMID 28640105, 2017). "Dabrafenib is an inhibitor of BRAF V600E used for treating metastatic melanoma but a majority of patients experience adverse effects." (PMID 28429064, 2017). "Combined targeted therapy with two kinase inhibitors is indicated for unresectable or metastatic melanoma, showing improved overall survival in combination compared to the BRAF inhibitor alone." (PMID 29088901, 2017). "Metastatic melanoma remains a fatal disease to many worldwide, even after the breakthrough introduction of targeted therapies such as BRAF inhibitors and immune checkpoint blockade therapies such as CTLA-4 and PD-1 inhibitors." (PMID 28435677, 2017). "In the case of patients who have BRAF-driven mutations, on 17 August 2011, the U S Food and Drug Administration (FDA) approved a new drug, vemurafenib (PLX4032), a selective BRAF inhibitor (BRAFi) for the treatment of advanced metastatic melanoma." (PMID 28708099, 2017). "Trametinib is indicated in the United States as a single agent and in combination with the BRAF inhibitor dabrafenib for BRAFV600E- or BRAFV600K-mutant metastatic melanoma." (PMID 28152546, 2017). "Despite the initial success of vemurafenib in treating patients with BRAF-mutant metastatic melanoma; resistance to therapy remains a challenge leading to disease progression in approximately 6 months." (PMID 29179510, 2017). "The first of these, trametinib, demonstrated an ORR of 22% vs. 8% for dacarbazine, and a median PFS of 4.8 months vs. 1.5 months (HR 0.45; 95% CI, 0.33–0.63; P < 0.001) in BRAF-mutant metastatic melanoma in the phase III METRIC trial." (PMID 29100459, 2017). "A phase 3 trial of binimetinib in combination with the BRAF inhibitor encorafenib (LGX818) for BRAFV600E-mutant metastatic melanoma is also ongoing (NCT01909453)." (PMID 28152546, 2017). "Subsequent efforts led to FDA-approval of BRAF inhibitors (BRAFi), vemurafenib and dabrafenib, against BRAF-V600E metastatic melanoma." (PMID 29156677, 2017). "Treatment of BRAF-mutant metastatic melanoma with mitogen-activated protein kinase (MAPK) pathway targeted therapies (BRAF/MEK inhibitors) has improved outcomes and revolutionized disease management for patients with advanced stage disease." (PMID 29113311, 2017). "This phase I study tested the safety and tolerability of the combination of vemurafenib and decitabine in metastatic melanoma patients, treatment naïve or previously treated with other agents including BRAF inhibitors." (PMID 29179510, 2017). "A phase 2 trial is underway to evaluate long-term efficacy of intermittent dosing (2 weeks on, 2 weeks off) of BRAF inhibitor LGX818 in patients with BRAF mutant metastatic melanoma (NCT01894672)." (PMID 29179523, 2017). "In conclusion, we have shown that RAF265, an orally available RAF/VEGFR‐2 inhibitor, produces clinical and metabolic responses in a subset of patients with locally advanced or metastatic melanoma, including patients with BRAF‐WT disease." (PMID 28719152, 2017). "Vemurafenib is a BRAF (v-raf murine sarcoma viral oncogene homolog B1) enzyme inhibitor for the treatment of patients who have metastatic melanoma." (PMID 28684722, 2017).
metastatic melanoma (continued). "We previously reported a patient with synchronous BRAF-mutated metastatic melanoma and BRAF wt /KRAS G12D-metastatic colorectal cancer (CRC), whose CRC relapsed and progressed when treated with the BRAF inhibitor dabrafenib (GSK2118436)." (PMID 28659148, 2017). "Novel targeted therapies for metastatic melanoma were rationally design, like BRAF inhibitors and modulators of the immune response that interfere with T-cell function." (PMID 28460440, 2017). "Selumetinib plus docetaxel in previously treated patients with KRAS-mutant advanced non-small cell lung cancer (NSCLC), and selumetinib plus dacarbazine in patients with BRAF-mutant metastatic melanoma, have more recently been assessed in phase II trials." (PMID 28264648, 2017). "Nivolumab (Opdivo) received expedited approval in 2014 for the treatment of BRAF V600 wild-type unresectable or metastatic melanoma as a single agent or in combination with ipilimumab." (PMID 29900022, 2017). "The discovery of the BRAFV600E mutation led to the development of vemurafenib (PLX4032), a selective BRAF inhibitor specific to the kinase, for the treatment of metastatic melanomas." (PMID 28708099, 2017). "Based on the critical need for effective new treatment approaches for patients with BRAF‐mutant and BRAF‐WT locally advanced or metastatic melanoma, we conducted this first‐in‐human phase I study of RAF265 in this treatment population." (PMID 28719152, 2017). "In this report, we present a retrospective study of the efficacy of Melphalan hypoxic perfusion in patients with pelvic metastatic melanoma stratified for prognostic factors, including BRAF." (PMID 29120401, 2017). "The rising epidemic of BRAF inhibitor resistance, as a consequence, invokes increasing combinatorial strategies for treatment of BRAF-mutant metastatic melanoma." (PMID 29179523, 2017). "There have been remarkable advances recently in the treatment of patients with metastatic melanoma, including the development of inhibitors to immune checkpoint proteins and targeted therapies against the protein kinases BRAF and MEK." (PMID 28103611, 2017). "Despite improvements in progression-free survival, most patients with BRAF-mutant metastatic melanoma still demonstrated disease progression within months following treatment with BRAF or MEK inhibitor monotherapy due to development of resistance." (PMID 29100459, 2017). "It is important to note, that the introduction of new therapeutic strategies for metastatic melanoma, such as BRAF/MEK inhibition and immune checkpoint blockade, is unlikely to be the reason for the failure of the present trial." (PMID 29100289, 2017). "The BRAF inhibitor vemurafenib was the first approved targeted therapy for BRAFV600E metastatic melanoma, achieving a response rate of 50% to 60% and significantly improving progression-free survival (PFS) and overall survival (OS)." (PMID 28147313, 2017). "Although mutant BRAF targeted-therapy and immunotherapy are showing exciting clinical results, the 5-year survival rate for patients with distant metastatic melanoma is merely 17%4." (PMID 28596565, 2017). "Recently, two highly selective MEK inhibitors, namely trametinib (Trame) and cobimetinib (Cobi), have been introduced, either alone or in combination with BRAF inhibitors, in the treatment of advanced cancers, including metastatic melanoma." (PMID 29064427, 2017). "There are two BRAF inhibitors, which are widely used for systemic treatment in metastatic melanoma: vemurafenib and dabrafenib." (PMID 28350340, 2017). "Other treatment options for metastatic melanoma include dabrafenib, another BRAF inhibitor used specifically in patients with the BRAFV600E mutation, as well as trametinib, a MEK1/2 inhibitor used specifically in patients with the BRAFV600E/K mutation." (PMID 27843913, 2016).
metastatic melanoma (continued). "The current therapeutic modality for mutant BRAF metastatic melanoma is treatment with BRAF inhibitors vemurafenib or dabrafenib in combination with MEK inhibitors for suitable patients." (PMID 27835901, 2016). "Vemurafenib is a type I1⁄2 BRAF inhibitor that is FDA-approved for the treatment of highly prevalent BRAF-V600E dependent metastatic melanomas." (PMID 27861609, 2016). "Finally, given that combined inhibition of BRAF/MEK is associated with improved clinical outcomes among patients with BRAF V600-mutated metastatic melanoma, we further assessed whether the addition of IL-18 to IL-15 was also able to rescue NK suppression induced by BRAF/MEK co-inhibition." (PMID 27563819, 2016). "BRAF inhibitors including vemurafenib and dabrafenib, have provided unprecedented benefits for the treatment of metastatic melanoma." (PMID 27648299, 2016). "The prognosis of patients with metastatic melanoma is changing owing to the introduction of selective BRAF inhibitors combined with MEK inhibitors." (PMID 30459994, 2016). "In clinical practice the gold standard method to assess BRAF status in patients with metastatic melanoma is based on molecular assays." (PMID 27863476, 2016). "We analyzed a retrospective series of 64 metastatic melanoma samples, previously investigated for molecular BRAF status, using a fully automatized immunohistochemical method." (PMID 27863476, 2016). "With new systemic therapies becoming available for metastatic melanoma such as BRAF and PD-1 inhibitors, there is an increasing demand for methods to assist with treatment selection and response monitoring." (PMID 26815318, 2016). "Recent advances in molecular profiling of tumors and immunotherapy have led to the development of new FDA-approved agents for metastatic melanoma, including the immune-checkpoint inhibitor, ipilimumab, and the BRAF inhibitor, vemurafenib." (PMID 27843913, 2016). "The selective BRAF inhibitors vemurafenib and dabrafenib yield high response rates and improved overall survival in patients with BRAF V600E-mutant metastatic melanoma." (PMID 26857260, 2016). "Here, we present organ‐specific efficacy and resistance data from a single‐institution retrospective analysis of BRAF V600‐mutant metastatic melanoma patients with progression on vemurafenib." (PMID 26414886, 2016). "For example, BRAF inhibitors were shown to improve OS and PFS in patients with metastatic melanoma that had the BRAF V600E mutation." (PMID 27842521, 2016). "Macrophages are also involved in metastatic melanoma resistance to chemotherapy with BRAF inhibitors." (PMID 27788481, 2016). "Patients with metastatic melanoma resistant to treatment with BRAF inhibitor or immunotherapy, are treated with DTIC, a TMZ analog." (PMID 27344172, 2016). "Studies investigating the combination of BRAF inhibitors and immunotherapy in the treatment of metastatic melanoma are ongoing." (PMID 26857260, 2016). "The benefits/risks of BRAF inhibitors followed by immunotherapy should be evaluated further in light of continuing developments in treatment options for metastatic melanoma." (PMID 27532019, 2016). "Vemurafenib and dabrafenib are two BRAF inhibitors (BRAFi) that have been licensed by FDA for the treatment of metastatic melanoma with mutant BRAF V600." (PMID 27042173, 2016). "A phase 3 trial has shown improved progression-free and overall survival in previously untreated metastatic melanoma containing BRAF V600E when compared to dacarbazine chemotherapy." (PMID 26989536, 2016). "Later, in 2015, the FDA additionally expanded an approval of nivolumab with BRAF wild-type and pembrolizumab for first treatment of unresectable or metastatic melanoma, each." (PMID 26899259, 2016). "Later FDA has approved the combination of dabrafenib and trametinib for the treatment of patients with BRAF V600E/K-mutant metastatic melanoma and their use seems to be currently the best approach." (PMID 27461275, 2016).
metastatic melanoma (continued). "Here, we retrospectively review imaging of 68 consecutive unselected patients with BRAF V600‐mutant metastatic melanoma for organ‐specific response and progression on vemurafenib." (PMID 26414886, 2016). "It is also used in combination with ipilimumab in patients with BRAF V600 wild-type unresectable or metastatic melanoma." (PMID 28090370, 2016). "The high recrudescence of metastatic melanoma following the treatment with BRAF inhibitors will potentially require combination therapies that activate additional tumour-inhibitory pathways." (PMID 26355347, 2015). "Positive results were also seen with combined dabrafenib and trametinib in patients with BRAF V600E/K metastatic melanoma and encorafenib plus binimetinib in BRAFV600-mutant cutaneous melanoma." (PMID 26141621, 2015). "As an example, Vemurafenib (PLX 4032), a small molecule inhibiting specifically mutant BRAF-V600E, has been successfully used in metastatic melanoma patients." (PMID 26160848, 2015). "BRAFV600E allele frequencies in pretreatment tumor specimens were not significantly correlated with treatment outcomes in 76 patients with metastatic melanoma who were treated with BRAF inhibitors." (PMID 26498143, 2015). "In our report, we presented a case of an unexpectedly prolonged survival in a patient with metastatic melanoma involving the brain and leptomeninges with BRAF inhibitor-based therapy." (PMID 25962795, 2015). "A systematic literature review was conducted to identify randomized controlled trials (RCTs) of BRAF inhibitors as first-line treatments for unresectable or metastatic melanoma." (PMID 27069772, 2015). "We evaluated the cost-effectiveness of BRAF inhibitors and traditional chemotherapy for treatment of metastatic melanoma." (PMID 26171248, 2015). "Allele frequencies had no impact on PFS, OS, and objective response rates in the 76 patients with BRAFV600E-positive metastatic melanoma treated with BRAF inhibitors." (PMID 26498143, 2015). "Duration of response to BRAF inhibitors in metastatic melanoma has been recorded as ranging from 2 to 18 months." (PMID 25785246, 2015). "In particular, efforts have been focused on targeting mutant BRAF for treatment in patients with metastatic melanoma." (PMID 29061943, 2015). "Here, we report a patient with BRAF-mutant metastatic melanoma who had a great clinical response in the LMD and an unexpectedly long survival with BRAF inhibitor-based treatment." (PMID 25962795, 2015). "An update on overall survival (OS) from the Combi-D study of combined dabrafenib plus trametinib in patients with BRAF V600E/K metastatic melanoma was also reported." (PMID 26141621, 2015). "BRAF inhibitors are a class of targeted therapeutics approved for treating metastatic melanoma and have demonstrated significantly improved overall survival." (PMID 26136771, 2015). "In mice, AKT inhibition synergizes with vemurafenib to block tumor growth of BRAF-mutant metastatic melanoma." (PMID 26098773, 2015). "Much of the clinical research into agents such as BRAF or MEK inhibitors has been performed on V600E positive metastatic melanomas in adults." (PMID 25785246, 2015). "The combination of the two drugs is approved by the U.S. Food and Drug Administration (FDA) for the treatment of BRAF-mutant metastatic melanoma." (PMID 26018524, 2015). "Examples are imatinib, targeting a specific fusion protein of ABL kinase in chronic myeloid leukemia, and vemurafenib and dabrafenib, targeting a mutant form of the protein kinase BRAF in metastatic melanoma." (PMID 26018524, 2015). "Selective BRAF inhibitors, vemurafenib and dabrafenib, and the MEK inhibitor, trametinib, have been approved for treatment of metastatic melanomas with a BRAF p.V600E mutation." (PMID 26498038, 2015).